MST1 (macrophage stimulating 1)
Diseases named in the same sentence as MST1 in open-access papers (continued):
Sharing a sentence is not in itself a finding about the gene and the disease.
myocardial infarction (21 papers, 2013 to 2025). Gross necrosis of the myocardium, as a result of interruption of the blood supply to the area, as in coronary thrombosis. "Specifically, mice with a specific deficiency of MST1/2 in macrophages displayed impaired post-myocardial infarction repair compared to wild-type mice." (PMID 36467420, 2022). "IR induces activation of MST1 in mouse heart; however, after overexpressing dominant-negative MST1 (DN-MST1), the inactive MST1 induces reduction in myocardial infarction (MI) size in areas at risk of mouse heart." (PMID 32390875, 2020). "In a myocardial infarction (MI) model using Mst1 transgenic (Tg) and Mst1 knockout (Mst1−/−) mice, luteolin treatment enhanced autophagy in Mst1Tg mice experiencing MI but did not increase autophagy in Mst1−/− myocardial cells." (PMID 40242436, 2025). "Mst1 inhibition has been shown to reduce cardiomyocyte apoptosis and improve cardiac function in response to myocardial infarction." (PMID 38195835, 2024). "The area of myocardial infarction (MI) was significantly smaller in Tg-Mst1 hearts than in WT hearts." (PMID 39060225, 2024). "It has been reported that Mst1 can promote cardiac dysfunction in myocardial infarction mice by inhibiting autophagy." (PMID 37005605, 2023). "Recent studies have shown that Mst1 signaling regulates many cardiovascular diseases, including the aortic dissection, aortic aneurysm, atherosclerosis and myocardial infarction ischemic injury." (PMID 37005605, 2023). "Overexpression of MST1 in mice can lead to increased cardiomyocyte death, left ventricular fibrosis, and deterioration of cardiac function following myocardial infarction." (PMID 38049831, 2023). "Consistent with the observations in Mst1 and Mst2 mouse models, genetic inhibition of Lats2 using a dominant negative mutant attenuated apoptosis and improved the phenotype following myocardial infarction in mice." (PMID 31328787, 2019). "This information shows that Mst1 was activated by myocardial infarction and contributed to cardiac dysfunction." (PMID 29760744, 2018). "Western blotting was used to observe the change in Mst1 expression after myocardial infarction (MI)." (PMID 29760744, 2018). "Further investigation into the intricate crosstalk between Mst1 and these pathways may pave the way for the development of novel therapeutic strategies for myocardial infarction and heart failure." (PMID 39006833, 2024). "Further investigation into the precise mechanisms by which Mst1 regulates these processes may pave the way for the development of novel therapeutic strategies for myocardial infarction and heart failure." (PMID 39006833, 2024). "Further investigation into the intricate mechanisms of Mst1 signaling may pave the way for novel therapeutic interventions for myocardial infarction and heart failure." (PMID 39006833, 2024). "Likewise, inhibition of Mst1 by expressing a dominant negative mutant form of this kinase reduced apoptosis and protected against cardiac dysfunction following myocardial infarction." (PMID 31328787, 2019). "Mst1 is also activated in response to I/R injury, myocardial infarction, and pressure overload." (PMID 31632964, 2019). "Based on this conclusion, novel therapeutic approaches that regulate the balance between the Mst1 level and mitochondrial homeostasis may improve the prognosis of patients after a myocardial infarction." (PMID 29760744, 2018). "In macrophages, deficiency in Mst1/2 worsens cardiac dysfunction after myocardial infarction, as mice lacking Mst1/2 in their macrophages exhibited a marked increase in left ventricular end-diastolic and end-systolic volume and decrease in ejection fraction and fractional shortening." (PMID 36467420, 2022). "However, suppression of endogenous Mst1 with cardiac-specific overexpression of a dominant-negative form of Mst1 (Mst1K59R) inhibited cardiomyocytes apoptosis, reduced the extent of myocardial damage and improved cardiac function after I/R injury or myocardial infarction." (PMID 31632964, 2019).
myocardial infarction (continued). "Similarly, inhibition of MST1 prevented cardiomyocyte apoptosis and protected against cardiac dysfunction following myocardial infarction (MI)." (PMID 35327528, 2022). "During ischaemia-reperfusion injury or myocardial infarction, the Hippo-YAP pathway is activated and then activates Mst1 to increase caspase activation and cardiomyocyte apoptosis." (PMID 35359458, 2022). "However, little is known about the role of Mst1 in chronic cardiac injury after myocardial infarction (MI)." (PMID 29760744, 2018). "The Mst1 inhibition by luteolin leads to dephosphorylation of the Hippo pathway downstream transcription factors YAP/TAZ, which then enter the nucleus to activate mitochondrial biogenesis-related genes, improving mitochondrial function and thereby mitigating myocardial infarction injury." (PMID 40242436, 2025). "Suppression of Hippo signaling by overexpression of a dominant-negative mutant of Mst1 in the heart did not significantly affect heart function but improved myocardial outcome after myocardial infarction (MI)." (PMID 34205942, 2021). "Mst1 knockout mice could reverse FUNDC1 expression and markedly reduced the myocardial infarction (MI) size." (PMID 31781358, 2019).
diabetic cardiomyopathy (20 papers, 2018 to 2025). Diabetic cardiomyopathy is a disorder of the heart muscle in people with diabetes. "Consistent with this study's findings, specific knockout of the MST1 gene in diabetic cardiomyopathy mice promotes the autophagic flux process, as evidenced by increased levels of LC3‐II in the presence of Bafilomycin A1." (PMID 39413003, 2025). "In a diabetic cardiomyopathy mouse model, Mst1 knockout restored autophagy and protected against apoptosis in cardiomyocytes, protecting against diabetic cardiomyopathy." (PMID 37005605, 2023). "Parkin-dependent mitophagy activity is enhanced after Mst1 inhibition, and this confers protection against diabetic cardiomyopathy, liver fatty disease, and septic cardiomyopathy." (PMID 35656021, 2022). "This was consistent with a previous study on diabetic cardiomyopathy, where Mst1 inhibition by melatonin treatment activated Parkin translocation." (PMID 35656021, 2022). "Further evidence reveals that the inhibition of mitophagy by Mst1 is associated with SIRT3, whereas depletion of SIRT3 restores cardiac function when Mst1 is overexpressed in diabetic cardiomyopathy." (PMID 32292354, 2020). "Mst1 depletion attenuates LPS-induced cardiomyocyte death or diabetic cardiomyopathy and improves cardiac function via promoting Parkin-dependent mitophagy." (PMID 32292354, 2020). "By inhibiting Mst1, melatonin also increases the expression of Parkin and thus restores Parkin-mediated mitophagy to protect the heart from diabetic cardiomyopathy." (PMID 32292354, 2020). "A growing body of evidence suggests the involvement of the Mst1-Hippo pathway in cancer proliferation, cellular migration, cardiac ischemia reperfusion and diabetic cardiomyopathy." (PMID 29760744, 2018). "Excessive Mst1 activation aggravates acute ischemia reperfusion injury by augmenting cardiomyocyte oxidative stress, promotes cardiac hypertrophy by enhancing cardiomyocyte necrosis, and induces diabetic cardiomyopathy by inhibiting protective autophagy." (PMID 29760744, 2018). "In a study using the mouse model of diabetic cardiomyopathy, the results showed that melatonin inhibited the expression of p-Mst1 and Mst1, and up-regulated the autophagy in myocardial tissue of diabetic mice, suggesting that melatonin may exert its cardio protective effect by inhibiting Mst1." (PMID 37005605, 2023). "In diabetic cardiomyopathy (DCM), cyclic RNA cerebellar degeneration-associated protein 1 antisense (Circ-CDR1as) promotes cardiomyocyte apoptosis by activating the Hippo signaling pathway through significant inhibition of mammalian sterile 20-like kinase 1 (MST1) ubiquitination levels." (PMID 37372440, 2023). "In a diabetic cardiomyopathy mouse model, endogenous activation of melatonin may hamper the progression of diabetic cardiomyopathy by up-regulating cardiomyocyte autophagy through Mst1 inhibition." (PMID 37005605, 2023). "Inhibition of MST1, an upstream negative regulator of YAP, alleviates diabetic cardiomyopathy, implying the possibility that YAP plays a protective role in diabetic hearts." (PMID 39122698, 2024). "Melatonin protects diabetic cardiomyopathy through MST1/SIRT3 signaling pathway 37, while garlic protects diabetic cardiomyopathy from oxidative stress by enhancing SIRT3 activity." (PMID 35002528, 2022). "Melatonin protects against diabetic cardiomyopathy through MST1/SIRT3 signaling, and garlic protects patients with diabetic cardiomyopathy from oxidative stress by enhancing SIRT3 activity." (PMID 29643974, 2018). "MST1, however, not only inhibits YAP but also induces apoptosis through inhibition of BCL-xL and it would be of importance to further elucidate the roles of RhoA and its downstream effectors in diabetic cardiomyopathy." (PMID 39122698, 2024).
lung cancer (17 papers, 2012 to 2026). A malignant neoplasm involving the lung. "In hepatocellular carcinoma, colon cancer, lung cancer, breast cancer and glioma, downregulation of MST1/2 is associated with accelerated tumor progression." (PMID 41144784, 2026). "A recent whole genome sequencing study identified MST1 as one of potential lung cancer-associated gene mutations." (PMID 38049831, 2023). "The anticancer effects of MST1 have been reported for numerous types of cancer, including colorectal, breast and lung cancers." (PMID 32218280, 2020). "We also assessed the levels of total MST1/2 in breast and lung cancer cells overexpressing RASSF1A or RASSF1C and found that RASSF1A appears to enhance and RASSF1C appears to reduce MST1/2 protein levels compared to control." (PMID 24327924, 2013). "Similarly, deficiency of MST1/2 kinases restored cell death, lipid peroxidation, and ferroptosis caused by MISP depletion in lung cancer cells." (PMID 40019375, 2025). "MiR-762, MST1, LATS2, YAP mRNA and protein, TWIST1, and SMAD3 may be effective diagnostic biomarkers in both lung cancer patients and chronic inflammatory patients." (PMID 38589525, 2024). "MiR-762, MST1, LAT2, YAP mRNA and protein, TWIST1, SMAD3 may be effective diagnostic biomarkers in both lung cancer patients and chronic inflammatory patients." (PMID 38589525, 2024). "It appeared that SAV1 stabilized MST1 in both lung cancer cell lines, H2170 and HCC827." (PMID 35864957, 2022). "Besides MST1/2-mediated RASSF5 functions on cell proliferation and apoptosis, RASSF5 was also reported to function independently of ras or MST1/2 in lung cancer cells." (PMID 34681900, 2021). "However, our results also indicated that down-regulated expression of MST1 in many cancers, including lung cancer, gastric cancer, esophageal cancer and CRC." (PMID 29079854, 2017). "Thus, we assessed MST1/2 phosphorylation in breast and lung cancer cells overexpressing RASSF1A or RASSF1C." (PMID 24327924, 2013). "Therefore, we assessed the phosphorylation of MST1/2 in breast and lung cancer cells overexpressing RASSF1A and RASSF1C in the presence of TNF-α." (PMID 24327924, 2013). "Consequently, lncRNA AATBC may promote lung cancer migration by activating the Hippo pathway through the lncRNA AATBC/YBX1/MST1 axis." (PMID 39313797, 2024). "Taken together, the data here demonstrate that MST1/2 kinases are indispensable for MISP to activate YAP and promote tumor growth in lung cancer." (PMID 40019375, 2025). "This underscores the significance of MST1/2 kinases in the MISP‐mediated regulation of YAP and highlights their potential as therapeutic targets in lung cancer treatment." (PMID 40019375, 2025). "On the other hand, the expression of MST1, LATS2 and the concentration of YAP protein were significantly downregulated in lung cancer patients (P = 0.008, 0.008, 0.001, respectively) as well as chronic inflammatory patients (P ˂ 0.001)." (PMID 38589525, 2024). "NSE protein is superior to YAP protein followed by miR-762, MST1, TWIST1, YAP gene, LATS2, and SMAD3 for the prediction of lung cancer." (PMID 38589525, 2024). "The relative expression of miR-762, MST1, LATS2, YAP, TWIST1, and SMAD3 was determined in 50 lung cancer patients, 30 patients with chronic inflammatory diseases, and 20 healthy volunteers by real-time PCR." (PMID 38589525, 2024). "We observed that lycorine treatment markedly increased levels of SAV1 and activated MST1 in the Hippo pathway, but significantly decreased the level of oncogenic YAP in lung cancer tissues." (PMID 32439835, 2020). "Overexpression of RASSF1C in breast and lung cancer cells reduced the effects of TNF-α on cell proliferation, apoptosis, and MST1/2 phosphorylation, while overexpression of RASSF1A had the opposite effect." (PMID 24327924, 2013). "We found that, while RASSF1A overexpression induced MST1/2 phosphorylation, RASSF1C overexpression attenuated MST1/2 phosphorylation in breast and lung cancer cells after TNF-α treatment." (PMID 24327924, 2013).
lung cancer (continued). "Subsequently, RASSF1A-induced autophosphorylation of MST1 and MST2 was analyzed in A549 lung cancer cells." (PMID 22577552, 2012). "In lung cancer patients, there were significant negative correlations between miR-762 and each of MST1, LATS2, and YAP protein (P = 0.048, 0.010, ˂ 0.001, respectively)." (PMID 38589525, 2024). "Western blotting showed that lycorine treatment not only markedly increased SAV1 protein levels but also dramatically increased phosphorylation of its interacting protein MST1, indicating MST1 protein activation, in SPC-A-1 and A549 lung cancer cells in a concentration-dependent manner." (PMID 32439835, 2020). "Lycorine treatment did not change total MST1 protein levels or SAV1 mRNA levels in these lung cancer cells." (PMID 32439835, 2020). "Here we found that the small molecule lycorine notably increased SAV1 levels in lung cancer cells by inhibiting SAV1 degradation via a ubiquitin–lysosome system, and inducing phosphorylation and activation of the SAV1-interacting protein mammalian Ste20-like 1 (MST1)." (PMID 32439835, 2020). "MiR-762 has a significant negative correlation with MST1, LATS2, and YAP protein in lung cancer patients and with MST1 and LATS2 in chronic inflammatory patients." (PMID 38589525, 2024).
pancreatic cancer (17 papers, 2015 to 2025). "In pancreatic cancer cells, MST1 overexpression inhibits mitophagy, promoting the activation of mitochondria‐dependent apoptotic pathways and reducing cell migration." (PMID 39413003, 2025). "This pattern was particularly evident for MST1, which exhibited cytoplasmic staining in the vast majority of the cases, aligning with findings in pancreatic cancer cells." (PMID 40649713, 2025). "In pancreatic cancer, TNF receptor-associated factor 6 increased the degradation of MST1 via the ubiquitination degradation pathway, overexpressed YAP and regulated tumor cell growth and metastasis." (PMID 38589525, 2024). "MST1 was found to inhibit pancreatic cancer progression through ROS-induced pyroptosis in pancreatic cancer." (PMID 35085103, 2022). "Immunohistochemistry studies in pancreatic tumour tissues revealed a significant upregulation of MST1, MST2, pLATS, pYAP and 14-3-3, representing the active Hippo pathway, in non-metastasized patients (p < 0.01)." (PMID 33098447, 2021). "We then explored the functional significance of Hippo signaling in the chemoresistance of pancreatic cancer cells by silencing of the two key kinases MST1 and LATS2." (PMID 26561204, 2015). "In summary, our study has revealed that miR-181c upregulation plays an important role in pancreatic cancer progression and miR-181c is a critical repressor of Hippo signaling by targeting the core kinase cassette, i.e., MST1, LATS2, SAV1 and MOB1." (PMID 26561204, 2015). "In pancreatic cancer, miR-181-c is significantly upregulated, correlates with a worse prognosis, and represses the Hippo pathway by directly repressing LATS2, MOB1, MST1, and SAV1, promoting pancreatic cancer cell survival and chemoresistance." (PMID 34575852, 2021). "We found that with the prolong of effect time of 8 mg/ml SJAMP on the pancreatic cancer cells, YAP, TEAD1, and Survivin expression significantly decreased, but the levels of the Hippo upstream gene, MST1, and Caspase-9 increased." (PMID 28099921, 2017). "Herein, we demonstrated that miR-181c was substantially overexpressed in pancreatic cancer and induced hyper-activation of YAP/TAZ via directly targeting MST1, LATS2, SAV1 and MOB1." (PMID 26561204, 2015). "MST1 or LATS2 silencing protected the apotosis induced by gemcitabine, and rendered pancreatic cancer cells to form more colonies in the presence of gemcitabine." (PMID 26561204, 2015). "Herein, we reported that miR-181c directly repressed MST1, LATS2, MOB1 and SAV1 expression in human pancreatic cancer cells." (PMID 26561204, 2015). "miR-181c directly repressed MST1, LATS2, MOB1 and SAV1, leading to YAP/TAZ activation and subsequent promotion of pancreatic cancer cell survival and chemoresistance in vitro and in vivo." (PMID 26561204, 2015). "Therefore, we examined the effects of PR55α on the core members of this pathway (MST1/2, MOB1, and LATS1/2) in pancreatic cancer cells using Dox-inducible shRNAs." (PMID 31659153, 2019). "Our results suggest that MST1/2 and LATS1/2 protein did not change markedly based on modulation of GPRC5A expression, which indicated that the regulation of YAP1 by GPRC5A is independent of LATS1/2 kinase in pancreatic cancer cells." (PMID 36735162, 2023).